INS (insulin)
Diseases named in the same sentence as INS in open-access papers (continued):
Sharing a sentence is not in itself a finding about the gene and the disease.
type 1 diabetes (continued). "Type 1 diabetes (T1D) is a well-studied prototypic tissue-specific autoimmune disease resulting from auto-reactive lymphocyte destruction of the pancreatic islet insulin-producing β-cells." (PMID 26378585, 2015). "Type 1 diabetes mellitus (T1DM) is an autoimmune disease manifest by progressive T cell-mediated autoimmune destruction of insulin-producing beta cells in the pancreatic islets of Langherans." (PMID 25788897, 2015). "Type 1 diabetes (T1D) is a metabolic disease that results from the autoimmune attack against insulin-producing β-cells in the pancreatic islets of Langerhans." (PMID 25604067, 2015). "In human pancreata, the abundance of α-cells compared to β-cells could lead to a functional excess glucagon secretion compared to insulin secretion and ultimately contributes to early clinical presentation in human type 1 diabetes, as advanced by Dr. Roger Unger and others." (PMID 26057531, 2015). "Type 1 diabetes (T1D) is a chronic autoimmune disease characterized by the selective destruction of insulin-producing beta-cells by the immune system." (PMID 26339637, 2015). "Therefore we determined if this alkaloid could in any way ameliorate the levels of testosterone and insulin in alloxan-treated type 1 diabetes-induced rats." (PMID 25695047, 2015). "A decreased PAH transport mediated by Oat1 and 3 transporters was also shown in type 1 diabetes mellitus (T1DM) rats and mice, and insulin treatment was able to restore their functions." (PMID 25883984, 2015). "However, it may result in less variable absorption and could be used in young children with type 1 diabetes undergoing closed-loop insulin delivery." (PMID 25537835, 2015). "Additionally, other factors that also increase the risk of IIH in children with type 1 diabetes should be considered, duration of type 1 diabetes, alterations in dose and type of insulin, insulin injection regime, and exercise, and belong to disadvantaged minorities." (PMID 24790575, 2014). "We hypothesize that a general mechanism by which the diseases and drugs identified in our study may trigger the clinical presentation of type 1 diabetes is that these conditions can change the state of metabolism and thereby increase insulin requirement in the body." (PMID 24498320, 2014). "Therefore, it is important to intensify monitoring and education of the child with type 1 diabetes submitted to insulin therapy, seeking to reduce the risks of hypoglycemia, particularly nocturnal hypoglycemia, hypoglycemia associated with exercise, and IIH during pregnancy." (PMID 24790575, 2014). "Interestingly, insulin inhibits apoptosis and furthermore tight glycemic control accomplished with exogenous insulin or pancreatic transplantation attenuates and/or reverses type 1 diabetes-induced pulmonary function abnormalities." (PMID 24423257, 2014). "However, physiologic insulin replacement remains necessary in patients with type 1 diabetes." (PMID 24668543, 2014). "In addition, the technology was used to develop a staff recall system for use after mass casualty incident and to develop a support system to enhance self-efficacy, facilitate uptake of intensive insulin therapy and improve glycemic control in pediatric patients with type 1 diabetes." (PMID 25099368, 2014). "In addition, new-onset type 1 diabetes or discontinuation of insulin in established type 1 diabetes (due to fear of weight gain, hypoglycemia, rebellion against constituted authority, and the stress of chronic disease) commonly leads to the development of DKA (21 percent)." (PMID 25945127, 2014). "The conversion of differentiated cells into insulin-producing cells is a promising approach for the autologous replacement of pancreatic cells in patients with type 1 diabetes (T1D)." (PMID 24963634, 2014).
type 1 diabetes (continued). "Therefore, the fact that hypoglycemia causes brain damage and cognitive deficit in adults significantly reinforces the argument presented by studies in children with type 1 diabetes on insulin therapy, the majority of whom suggest the existence of cognitive compromise associated with IIH." (PMID 24790575, 2014). "Type 1 diabetes mellitus (T1D) is an autoimmune disease in which pancreatic β cells are destroyed, generating an incapacity to maintain appropriate insulin and glucose concentrations." (PMID 24594198, 2014). "Type 1 diabetes (T1D) is an autoimmune disease mediated by a combination of genetic and environmental triggers that is characterized by the progressive destruction of insulin-producing cells in the pancreatic islets by autoreactive T cells." (PMID 23671851, 2013). "Type 1 diabetes (T1DM) is frequently accompanied by dyslipidemia related with insulin-dependent steps of the intravascular lipoprotein metabolism." (PMID 23398881, 2013). "In addition, the melatonin-insulin interaction in type 1 diabetes is of interest." (PMID 23535335, 2013). "It is possible that the longer duration of type 1 diabetes among women using insulin glargine was due to women switching to the newer insulin glargine from established insulin regimens in order to achieve better glycemic control than that provided by their prior insulin therapy." (PMID 22685467, 2012). "Importantly the young type 1 diabetes individuals in the present study were insulin resistant despite any clinical characteristics of the metabolic syndrome and, therefore, enabled us to investigate the correlation between insulin sensitivity per se and cIMT." (PMID 23185996, 2012). "In the near future, this model could also be implemented to simulate and/or predict calcium signals and glucagon release by pancreatic -cells in pathological situations such as type 1 diabetes, which is characterized by a lack or very low concentrations of insulin and elevated glucose levels." (PMID 22412861, 2012). "This is the first qualitative study to explore in depth and over time type 1 diabetes patients’ views about, and need for, health professional and health service support after attending a structured education programme promoting flexible intensive insulin therapy." (PMID 22891794, 2012). "We presume a large proportion of the 19 managed with insulin were type 1, based on their age at diagnosis and the expected prevalence of type 1 diabetes (1 in 250), suggesting that there should be approximately 34 individuals with type 1 diabetes in the cohort." (PMID 22927834, 2012). "Type 1 diabetes mellitus (T1DM) is a complex disease characterized by autoimmune and progressive destruction of insulin secreting pancreatic β-cells." (PMID 23497668, 2012). "Type 1 diabetes mellitus (T1DM) results from selective elimination of the insulin-producing β-cells within the pancreatic islets via an autoimmune mediated process that requires infiltration of T-lymphocytes and activation of resident macrophages." (PMID 23056550, 2012). "The HypoAna Trial will elucidate whether basal-bolus regimen with short-acting and long-acting insulin analogues in comparison with human insulin are superior in reducing occurrence of severe hypoglycaemic episodes in hypoglycaemia prone patients with type 1 diabetes." (PMID 22727048, 2012). "Insulin-dependent, or Type 1 Diabetes Mellitus (T1D) results as a consequence of the specific autoimmune destruction of the pancreatic islet beta cells." (PMID 21738580, 2011). "Type 1 Diabetes (T1D) is an autoimmune disorder in which the body's own immune cells (cytotoxic T lymphocytes, CTLs) target the insulin-secreting beta cells in the Islets of Langerhans of the pancreas." (PMID 21573001, 2011).
type 1 diabetes (continued). "Some groups may be more vulnerable to psychiatric problems, such as teenage girls and women who are particularly prone to eating disorders and may omit insulin doses as a means of weight control, which can adversely affect optimal management and outcomes in type 1 diabetes." (PMID 20456170, 2010). "In type 1 diabetes, protein turnover studies using isotopically labeled amino acid tracers have demonstrated that protein breakdown and amino acid oxidation are increased in the insulin-deprived state, and are normalized by insulin, which has an anticatabolic effect." (PMID 20721344, 2010). "There may be a misconception that intensive insulin therapy is not necessary at diagnosis and particularly in the ‘honeymoon period’ because of the residual β-cell function/insulin secretion that persists months after diagnosis in some individuals with type 1 diabetes." (PMID 20456170, 2010). "Type 1 diabetes mellitus (T1DM) is a multifactorial autoimmune disease in which T-lymphocytes infiltrate the islets of the pancreas and destroy the insulin-producing beta cell populations." (PMID 19768110, 2009). "Thus, we hypothesize that increased insulin gene transcription in beta cells during virus infection and/or during development of type 1 diabetes could generate dsRNA-like structures that augment 2′5′AS activity and contribute to beta cell apoptosis." (PMID 19888425, 2009). "In this randomized, double-masked, parallel study, 100 patients with type-1 diabetes, preserved hypoglycaemic awareness and persistent inadequate glycaemic control were treated for 12 months with either metformin or placebo as an adjunct therapy to ongoing insulin therapy." (PMID 18852875, 2008). "Pancreatic insulin-producing beta-cells are selectively destroyed by the immune system in type 1 diabetes mellitus (T1DM)." (PMID 17302974, 2007). "Phase 3 trials have demonstrated that INH is as efficacious as subcutaneously (SC) injected regular human insulin in type 1 diabetes (T1DM) or T2DM, and superior to OAs in T2DM." (PMID 16901335, 2006). "Furthermore (pro)insulin appears to be an autoantigen in the development of type 1 diabetes." (PMID 15679918, 2004). "While Type 1 Diabetes Mellitus (T1DM) can be diagnosed at any age, it is typically diagnosed during childhood and adolescence and requires lifelong insulin treatment." (PMID 40856153, 2026). "We included RCTs enrolling subjects with type 1 diabetes, evaluating commercial HCL systems against other insulin therapy regimens, with a duration of intervention ≥2 weeks, and reporting time in range (TIR) as an outcome." (PMID 41024422, 2026). "While CGM has been shown to be effective in patients with type 1 diabetes (T1D) and T2D, CGM is most commonly used in patients with T1D or patients with T2D on an intensive insulin regimen." (PMID 41601933, 2026). "Interestingly, patients who were positive for GADA, had low insulin requirements, and preserved C-peptide levels despite poor glycemic control, suggesting a transient phase of endogenous insulin secretion compatible with the honeymoon period of type 1 diabetes." (PMID 41367630, 2025). "As an addition to insulin, the GLP‐1 analog liraglutide lowers HbA1c and decreases body weight in type 1 diabetes." (PMID 40735262, 2025). "Because the mouse cannot generate insulin to lower blood glucose levels after STZ treatment, it is considered a model of type 1 diabetes." (PMID 40572277, 2025). "Type 1 Diabetes Mellitus (T1DM) is an autoimmune disorder characterized by pancreatic β-cells destruction and lifelong dependence on exogenous insulin." (PMID 41372973, 2025). "Modern technologies such as insulin pumps and continuous glucose monitoring (CGM) systems have become increasingly important in the management of type 1 diabetes particularly among children and adolescents." (PMID 41149081, 2025).
type 1 diabetes (continued). "Type 1 diabetes mellitus (T1DM) is one of the most common chronic autoimmune diseases, characterized by the destruction of pancreatic β-cells and the resulting inability to produce insulin." (PMID 41567899, 2025). "Immune dysfunction in type 1 diabetes refers to beta cell-directed autoimmunity, classically seen as an offensive attack from CD8+ T cells that detect autoantibodies from insulin-producing beta cells." (PMID 40553147, 2025). "Only one study in adolescent women (13–16 years old) with type 1 diabetes showed correlations between HRV indices and androgens (free androgen index FAI), sex hormone binding protein (SHBP), glucose levels, and insulin." (PMID 40267043, 2025). "Type 1 diabetes (T1D) is an autoimmune disorder where macrophages and CD4+ and CD8+ T cells infiltrate the islets of Langerhans, destroying insulin-producing β-cells." (PMID 39796264, 2025). "The presence of remaining insulin-positive cells in type 1 diabetes (T1D) is well-known." (PMID 38922355, 2025). "Our patient, initially misdiagnosed and managed as a case of type 1 diabetes, was found to have features suggestive of MODY and responded favorably to sulfonylurea therapy with complete insulin discontinuation." (PMID 40777711, 2025). "Type 1 diabetes (T1D) is a chronic autoimmune disease characterized by the T cell-mediated destruction of insulin-secreting pancreatic β cells, leaving patients reliant on exogenous insulin to establish normoglycemia." (PMID 41480350, 2025). "Type 1 diabetes (T1D) is a complex autoimmune disease where an autoimmune attack destroys the pancreatic islet beta cells, which eventually results in a complete dependency on exogenic insulin." (PMID 39989961, 2025). "Specifically, we focused on glucose-stimulated insulin secretion (GSIS) performed by islets of the pancreas, the failure of which leads to type I diabetes." (PMID 40267204, 2025). "Additionally, the management may include the management of type 1 diabetes with insulin and necessary hypoglycemic agents, hearing aid or cochlear implants for hearing loss, and supportive care to manage the overall spectrum of symptoms found in Rogers syndrome." (PMID 41210025, 2025). "Autoimmune diabetes, or type 1 diabetes mellitus (T1DM), is a chronic inflammatory disease characterized by an autoimmune reaction against pancreatic beta cells, hence leading to insufficient insulin production and hyperglycemia." (PMID 41472723, 2025). "For example, in patients with type 1 diabetes mellitus (T1DM) treated with T-regs, insulin requirements and C-peptide levels remained stable although no reduction in disease progression was observed." (PMID 39967659, 2025). "Advances in insulin analogues, insulin pumps and continuous glucose monitoring (CGM) systems have greatly improved glycaemic management in individuals with type 1 diabetes." (PMID 39888427, 2025). "We systematically collected and analysed all available evidence from RCTs directly comparing currently available insulin treatments, including HCL, AHCL, and FCL therapy, on the key outcomes of time in glycaemic ranges in people with type 1 diabetes." (PMID 40270713, 2025). "Type 1 diabetes (T1D), a chronic autoimmune disease, is characterized by the activation of autoreactive CD8+ T cells and autoantibodies that target and destroy insulin-producing β-cells in the pancreatic islets of Langerhans and insulin directly." (PMID 40607421, 2025). "Type 1 diabetes mellitus (T1DM) is an autoimmune disease that destroys pancreatic β-cells, impairing insulin secretion and poor glycemic control." (PMID 40264762, 2025). "This two-centre, open-label, crossover RCT investigated the glycaemic efficacy of HCL insulin therapy using the mylife CamAPS FX system with SMA vs CC in youth and young adults with type 1 diabetes." (PMID 39560745, 2025).
type 1 diabetes (continued). "At Children’s of Alabama, all patients with insulin dependent diabetes are considered for continuous subcutaneous insulin infusion therapy (CSII, also known as insulin pump)." (PMID 40538808, 2025). "This systematic review and meta‐analysis evaluated the efficacy and safety of the iLet bionic pancreas (iLet BP), a novel automated insulin delivery (AID) system, in managing type 1 diabetes." (PMID 41157817, 2025). "Type 1 diabetes (T1D) is an autoimmune disorder characterized by the destruction of pancreatic islet beta-cells, which leads to hyperglycemia, resulting in metabolic dysfunction that requires lifelong insulin administration." (PMID 40650727, 2025). "Type 1 Diabetes Mellitus (T1D) is a chronic autoimmune disease characterized by the loss of pancreatic beta-cells, which results in the eventual lack of insulin production and subsequent hyperglycemia." (PMID 41465739, 2025). "Therefore, we believe that the addition of the empagliflozin/metformin combination to insulin treatment could be beneficial in the group of people with type 1 diabetes characterized by increased weight, elevated cardiovascular risk, and poorly controlled glycemia." (PMID 39598003, 2024). "The present study reports on the safety of a unique user-initiated insulin delivery intensification mode (“Boost”) during eight weeks of home-use of the Cambridge HCL algorithm by children and adults with type 1 diabetes." (PMID 36475908, 2024). "This oral delivery method, at 50 IU/kg, attained a maximal plasma insulin level (50 mIU/mL) at 4 h, and it remained higher for 8 h in a BALB/c mouse type I diabetes model." (PMID 38167129, 2024). "With the growing focus on type 1 diabetes disease modulation and working towards an ‘insulin free T1D’, our findings strengthen the evidence base for the repurposing of and long-term treatment with anti-TNF-α agents to preserve beta-cell function in new onset T1D." (PMID 39252097, 2024). "One of the targets is 100% access to affordable insulin and SMBG devices for people living with type 1 diabetes." (PMID 39361609, 2024). "Progression to Stages 2 and 3 of type 1 diabetes increases with HOMA-IR and decreases with the Matsuda Index after adjustments for insulin secretion." (PMID 37914981, 2024). "This study aimed to investigate whether the response to adding metformin to insulin in young adults with type 1 diabetes (T1D) differs according to weight phenotype and insulin sensitivity index." (PMID 39218890, 2024). "The Omnipod® 5 Automated Insulin Delivery (AID) System was shown to be safe and effective following 3 months of use in people with type 1 diabetes (T1D); however, data on the durability of these results are limited." (PMID 37850941, 2024). "Serving as an adjunct to insulin, the double-acting inhibitor of SGLT1 and SGLT2, sotagliflozin can enhance the manage of blood glucose levels in patients diagnosed with type 1 diabetes." (PMID 38694909, 2024). "Type 1 diabetes, also termed insulin-dependent diabetes (IDDM), is an autoimmune illness that usually occurs in childhood or adolescence and is marked by the devastation of insulin-producing beta cells in the pancreas." (PMID 39737321, 2024). "In this article, we report real-world findings of the InPenTM smart insulin pen paired with CGM (InPen system), used by persons with type 1 diabetes (T1D) and type 2 diabetes (T2D)." (PMID 37855818, 2024). "Type 1 diabetes mellitus (T1DM) is a type of chronic autoimmune disease defined by the relative or absolute lack of insulin caused by either the destruction or the dysfunction of the body’s own pancreatic beta cells." (PMID 39767077, 2024). "The presence of IA-2 autoantibodies, along with insulin and GAD, strongly correlated with the incidence and rapidity of type 1 diabetes onset." (PMID 39211046, 2024).